KRAS (KRas proto-oncogene, GTPase)
Diseases named in the same sentence as KRAS in open-access papers (continued):
Sharing a sentence is not in itself a finding about the gene and the disease.
tumor (continued). "Regardless of KRAS status in tumor tissues, patients with MctDNA in blood showed poor progression-free survival with first-line treatment." (PMID 29849949, 2018). "KRAS mediates signal transduction between membrane growth factor receptors and downstream pathways, such as PI3K/AKT/mTOR and RAS/RAF/MEK/ERK, which all contribute to tumor growth, progression, and metastasis." (PMID 29386069, 2018). "Manipulation of KRAS signalling did not result in obvious enhancements of tumour cell proliferation or survival in vitro; on the contrary, overexpression of KrasG12C2A in PANO2 cells and of KrasG12C2B in B16F10 cells slowed their growth rate." (PMID 28508873, 2017). "In primary CRC clinical specimens, we found that ASCT2 expression was significantly associated with tumor depth and vascular invasion in KRAS-mutant CRC, but not in wild-type KRAS CRC." (PMID 28749408, 2017). "Conversely, average tumour volume of KRAS wild-type cells with FOSL1 inhibition did not change compared to the control group." (PMID 28220783, 2017). "Several investigators have assessed circulating tumor DNA (ctDNA) in the blood of mCRC patients during anti-EGFR therapy and found that undetectable low-frequency KRAS-mutant clones may be selected by anti-EGFR treatment." (PMID 28368335, 2017). "Compared with alveolar cells, bronchiolar epithelia cells are close-packed and express polarity-related protein specifically located on apical or basal, which function as a non-cell-autonomous tumor suppressor to restrict KRAS-induced cell proliferation." (PMID 28871124, 2017). "Enrichment for genes that function in the epithelial-mesenchymal transition, KRAS signaling, hypoxia, and apoptosis was also seen in the Huh-6 tumor sample, and these changes were not seen in either HepG2 sample." (PMID 29259231, 2017). "The lack of mutations in KRAS, EGFR and ALK genes in CRC cultured tumor specimens suggested that the cells growing in CRC conditions are mostly non-malignant." (PMID 28052041, 2017). "The tumor tissue was defined as KRAS exon 2–4 wild type prior to 1st line therapy and no further tissue analyses were done according to standard clinical practice." (PMID 28328955, 2017). "This tumor was EGFR (epidermal growth factor receptor), ALK (anaplastic lymphoma kinase), KRAS (V-Ki ras2 Kirsten rat sarcoma viral oncogene homolog), ERBB2 (erb-b2 receptor tyrosine kinase 2), and B-Raf (V-raf murine sarcoma viral oncogene homolog B1) wild-types." (PMID 28915906, 2017). "Although KRAS is a negative predictive marker, not all patients with wild-type KRAS in tumor cells respond to EGFR-targeted therapies." (PMID 28468669, 2017). "AXIN2+DKK1 methylation significantly predicted recurrence independent of age, sex, tumor size, localization, differentiation, CIMP, BRAF and KRAS mutations." (PMID 28368388, 2017). "On the other hand, in the protein expression profile of SSC-2, the neoplastic proliferation of tumor cells was related to the overexpression of PCNA, MPM2, KRAS, STAT3, EGFR, and bFGF and was supported by the overexpression of the protein translation factors eIF5A, DHS, and DOHH compared to SSC-1." (PMID 28789700, 2017).
tumor (continued). "However, the model of KRAS and Lkb1 is actually a mixed histology model, containing ADC, SCC and mixed ADSCC tumours." (PMID 28387316, 2017). "CNVs in tumour cells also enhance proliferation, albeit at the expense of the host; for example, copy number amplification can drive tumour growth (e.g., of FGFR2 or CDK4) or mediate drug resistance (e.g., of DHFR, KRAS or BRAF)." (PMID 28654659, 2017). "A large body of evidence indicates that inhibition of oncogenic KRAS by either genetic (shRNA) or pharmacological approaches delays, but does not prevent, tumor growth due to the ineffective induction of cell death." (PMID 28152508, 2017). "The data we have present also indicate that it may not only be the KRAS and EGFR status itself, but rather the quantitative amount of cfDNA derived from tumor that influences the disease behavior." (PMID 28382702, 2017). "Interference with mitochondrial respiration using oligomycin at doses used previously in vitro and in vivo to block OXPHOS indeed resulted in markedly reduced numbers of tumor spheroids in both control and RANKL-stimulated KRas;rank+/+ cells in a dose-dependent fashion." (PMID 29118048, 2017). "The knockdown of both KRAS and NRP1 in PANC-1 cell lines (KRASmt) inhibited tumor formation." (PMID 29018205, 2017). "Intratumoral expression of CXCL9 and CXCL10 was significantly reduced in tumors from compound mutant RasApc mice, but not in single transgenic mice expressing oncogenic KRAS, which display lower tumor number and mortality." (PMID 29163806, 2017). "We observed that KRAS transplant tumours had very few Sca1+/NGFR+ cells and were indistinguishable from adeno-Cre induced KRAS tumours (P=0.368)." (PMID 28387316, 2017). "In this case an assay detecting circulating mutant KRAS simply detects more tumor; it does not explain drug tolerance." (PMID 28981524, 2017). "At face value, these data suggested that MYC is not essential for treatment response in KRAS mutant tumor cells." (PMID 28152508, 2017). "We previously reported that wild-type KRAS is one of the downstream effector molecules of NRP118, which could mediate its opposing functions in tumor growth and progression." (PMID 29018205, 2017). "Based on these results, it could be inferred that targeting glucose metabolism in CRC patients bearing KRAS- or BRAF-mutant tumors may be a safer and more effective strategy compared to utterly impairing tumor angiogenesis." (PMID 28445144, 2017). "In support of this hypothesis, cells stably over-expressing PDHK4 exhibited an increase in KRAS activity and 3D cell growth in vitro and in vivo, suggesting a role for PDHK4 in the growth of KRAS mutant tumours." (PMID 28692044, 2017). "This has been successfully used for CTCs isolated by other techniques but one group also reported non-matching KRAS status between tumor and CTCs in some cases." (PMID 29156783, 2017). "It is possible that these engineered models do not fully replicate all of the KRAS synthetic lethal effects found in real human tumours." (PMID 26881434, 2016). "RQI results were compared to patients’ age and sex, tumor site, kind of surgery, anastomosis failure, adenocarcinoma type and grade, tumor cell percentage, necrosis extent, HIF-1α and cleaved caspase-3 immunohistochemistry, and BRAF, KRAS and microsatellites status." (PMID 27124490, 2016).
tumor (continued). "MGMT methylation was detected in 17 of 64 (26.6%) patients, and was not correlated with sex, age, tumor differentiation, CIMP, MSI, or KRAS mutations." (PMID 27643594, 2016). "Our initial limited “targeted” analyses of PTEN, KRAS, BRAF, PI3KCA and MET did not elucidate predictors of response to MEK inhibitors with any tumor-specific genetic variants." (PMID 26683364, 2016). "Across all lines of therapy, determination of tumour RAS status improves identification of patients unlikely to respond to treatment with panitumumab compared with evaluation of KRAS exon 2 alone." (PMID 27764839, 2016). "It was reported that miR-126 was down-regulated in PC tissues and could act as a tumor suppressor in PC by inhibiting ADAM9, KRAS and CRK which was in accordance with our findings." (PMID 27626307, 2016). "The E6-E7-st-KRAS-shCXCR2 cells demonstrated a non-significant (NS) reduction in tumor growth compared to the E6-E7-st-KRAS-NSC cells." (PMID 26771140, 2016). "RAS (KRAS and NRAS) status may, however, differ between the primary tumor and metastatic lesions, due to intratumor heterogeneity and subclonal evolution." (PMID 27863403, 2016). "His tumour was wild type for EGFR, KRAS and ALK, but did display MET positivity by IHC." (PMID 26883990, 2016). "This study demonstrated that a left-sided primary tumor site is a useful predictive marker for improved cetuximab efficacy for the third-line or salvage treatment among patients with KRAS wild-type (exon 2 nonmutant) metastatic CRC." (PMID 27221731, 2016). "Nonetheless, tumor response to PIK3R2 depletion did not require PIK3CA, PTEN or KRAS mutation, and caused shrinkage of all tumors examined with enhanced p85β expression." (PMID 27835880, 2016). "In addition, haploinsufficiency of Tgfbr1 reduces the development of Kirsten rat sarcoma viral oncogene homolog (KRAS)-driven pancreatic precancer formation, uncovering a potential tumor promoting effect of TGFβ signaling." (PMID 27344183, 2016). "This relation between KRAS and YAP may have an implication in the development of novel therapies against RAS mutant tumours." (PMID 27322327, 2016). "To date, KRAS trans-regulatory factors have been primarily identified through computational predictions and large-scale CLIP-seq and RNA-IP profiling of cancer cell lines and human tumor samples." (PMID 26930719, 2016). "This analysis suggested that the CDK1/KRAS synthetic lethal effect was not restricted to isogenic systems but also operated in a variety of different, genetically diverse, KRAS mutant tumour cells." (PMID 26881434, 2016). "Our findings demonstrate that a left-sided primary tumor site is a useful predictor of improved cetuximab efficacy in the third-line or salvage treatment of KRAS wild-type (exon 2 nonmutant) metastatic CRC." (PMID 27221731, 2016). "Our data demonstrates that CXCR2 signaling mediates KRAS-induced PC growth and suggests that targeting CXCR2 signaling might be a feasible approach to inhibit KRAS(G12D)-induced PDAC tumor cell growth." (PMID 26771140, 2016). "It is currently unknown whether synergism of EGFR/KRAS and FLCN LOH accelerates tumor progression in the lung." (PMID 26974543, 2016).
tumor (continued). "In particular, RAC-1 and c-Raf appeared to be critical downstream (of KRAS) nodes in the MAPK pathway whose inhibition is not toxic per se, but blocks proliferation only in KRAS mutant tumour cells." (PMID 27350784, 2016). "Up-front tumor RAS testing—rather than solely KRAS exon 2 testing—is critical for patients with mCRC, as RAS mutations predict a lack of response to anti-EGFR therapy." (PMID 26573425, 2016). "Similarly, observations were reported in a previous study for KRAS and other gene mutations, however no reference was made as to the morphology of these lesions, which in liver and lung tend to be highly necrotic with a paucity of tumour cells for enrichment by microdissection." (PMID 27756406, 2016). "It showed superior in vivo efficacy compared to cetuximab and non-glycoengineered imgatuzumab in both KRAS-mutant and KRAS-wild type tumor models." (PMID 27602494, 2016). "The analysis in the non-isogenic tumour cell panel suggested that the CDK1/KRAS SL was a relatively hard synthetic lethal effect." (PMID 26881434, 2016). "Thus, when targeted NGS results were compared to results obtained by real-time PCR for tumor samples from patients with NSCLC, the two methods had high concordance rates for the three genes tested: 96.3% for EGFR, 98.7% for KRAS, and 100% for BRAF." (PMID 27589834, 2016). "In concodance to our in vitro results, H358 xenograft tumor expressing mutant KRAS showed significant effect neither to zoledronic acid nor cisplatin." (PMID 27780929, 2016). "Combination treatment demonstrated enhanced reduction in tumor growth against CRC cell line and patient-derived tumor xenograft models as compared to either single agent regardless of KRAS or PI3K mutational status." (PMID 26404261, 2015). "It has been proposed that oncogenic KRAS might promote tumor progression by limiting the efficacy of RAS/RAF/MEK/ERK1/2 signaling, whereas KRAS—responsive tissues exhibit a full activated signaling pathway, and trigger potent antitumor responses." (PMID 26110767, 2015). "The absence of macroheterogeneity, for example for KRAS and NRAS mutations, suggests that these drivers were acquired on the trunk of the phylogenetic tree, in tumours in which they are detectable." (PMID 25555261, 2015). "It is not suppressing that not all patients with wild type KRAS in the primary tumor are successfully treated with anti-EGFR antibodies." (PMID 25628770, 2015). "Beside KRAS status, progression free survival was independent of gender, age, site of primary tumor, presence of synchronous metastasis, and chemotherapy regimen." (PMID 25888291, 2015). "Additionally, gene amplifications of KRAS (32%), BRAF(30%), and EGFR (23%) are common to human BBCs and BBC cell lines and tumor models have been shown to exhibit an oncogenic Ras-like gene expression signature." (PMID 26497685, 2015). "Importantly, genes co-expressed with SLC16A7/MCT2 in human tumours also clustered in oncogenic-related pathways (e.g. PI3K, EGFR, KRAS) and effectors of these signalling pathways were found to bind at the SLC16A7/MCT2 gene locus (e.g. MYC, EGR1, PRDM1)." (PMID 26035357, 2015). "We hypothesized that mutant KRAS can regulate glutamine metabolism genes in NSCLC and maintain tumor redox balance through transamination reactions that generate cytosolic NADPH via malic enzyme 1 (ME1), which may contribute to radioresistance." (PMID 26173780, 2015). "This appeared to be due to lack of read coverage for KRAS in the other tumors sequenced, and we asked for re-evaluation of the tumor sections by a certified pathologist." (PMID 25594743, 2015).
tumor (continued). "Future experiments will include chronic rapamycin treatment of mice bearing the PTEN−/−, 10A-KRAS(G12V), and PTEN−/−KRAS(G12V) cells to determine if rapamycin can eliminate dormant cells and/or delay the tumor formation from the aggressive PTEN−/−KRAS(G12V) cells." (PMID 26497685, 2015). "Consistent with p63, p40 and AR-status in human SDCs, these oncogenic KRAS-expressing sarcomatoid tumor cells were negative for the expressions of these markers." (PMID 26289340, 2015). "Considering that a higher percentage of patients with a mutant KRAS tumor did not even underwent third-line treatment compared to wild-type we do not find these results in contrast with those previously reported by our group." (PMID 26416458, 2015). "There was also a very good level of knowledge amongst oncologists around the need to test and confirm wild-type KRAS tumor status prior to treatment with panitumumab, with or without concurrent oxaliplatin-containing therapy." (PMID 26491871, 2015). "Comparison of the genome of this tumor, CB42, with genomes from non-propagating tumors by array CGH and sequencing revealed an amplicon on chromosome five containing CDK6 and CDK14, and a KRAS mutation, respectively." (PMID 25162504, 2014). "Recent trials have shown that patients with KRAS mutant tumours do not respond to anti-EGFR agents (cetuximab/panitumumab) because the activating mutation occurs downstream from the target of anti-EGFR therapy." (PMID 25361007, 2014). "Clinically, patients with KRAS wild-type tumours are more likely to respond to anti-EGFR therapy whereas those with mutant KRAS show lack of benefit." (PMID 24720724, 2014). "PCR-based DNA sequencing analysis of the patient’s tumor specimen revealed no EGFR, BRAF, KRAS, PI3KCa, or c-kit mutations." (PMID 25126591, 2014). "Ectopic introduction of miR-96, but not miR-181, decreased KRAS protein expression and resulted in cell cycle arrest in cells, suggesting miR-96 as a tumor suppressor in EVI1-mediated KRAS regulation." (PMID 25433809, 2014). "Although the Ras oncogene promotes glycolysis in many cells and tumor contexts, our metabolomic results and extracellular lactate levels gave no clue to significantly heightened glycolysis in these KRAS mutants." (PMID 24952473, 2014). "In patients with a KRAS wild type tumor the median OS for non-users compared to statin users was 22.4 vs. 19.8 months and in the KRAS mutant tumor group the OS was 18.1 vs. 14.5 months." (PMID 25375154, 2014). "Also identified were four rare tumor cells that showed a 50-fold amplification of the KRAS (Kirsten rat sarcoma viral oncogene homolog) locus that was absent in the major tumor subpopulations, suggesting that the most malignant populations in the tumor might also be the rarest." (PMID 25222669, 2014). "Oncogenic RAS co-operates with other oncoproteins, as in the case of requirement for interaction of PI3-kinase p110α with RAS in lung tumour maintenance, or the study where single copies of mutant KRAS and mutant PIK3CA cooperate in immortalized human epithelial cells to induce tumour formation." (PMID 25361007, 2014). "Tumor growth inhibition with BKM120 was modest in this study and may be explained by the primary tumor being PI3KCA wild type and KRAS mutant." (PMID 24586805, 2014). "In contrast, an infiltrating tumor growth pattern is significantly more frequent in tumors with activating BRAF-mutations, while no impact of KRAS-mutations was observed." (PMID 24600585, 2014). "The tumor cells that harbored the KRAS amplification intermixed with those that did not, suggesting that genetically distinct tumor populations do not necessarily segregate spatially." (PMID 25928070, 2014). "In patients with a KRAS wild type tumor (n = 321) the median PFS was 10.3 vs. 11.4 months for non-users compared to statin users and in patients with a KRAS mutant tumor (n = 208) this was 7.6 vs. 6.2 months, respectively." (PMID 25375154, 2014).